RNU6-597P (RNA, U6 small nuclear 597, pseudogene)
Gene: Small nuclear RNA gene on chromosome 14 (63,618,043 to 63,618,144, forward strand). Ensembl gene ENSG00000202490.
Homologues: Orthologues: chimpanzee U6 (99% identical), macaque U6 (90% identical). Paralogues in human: RNU6-1251P (88% identical), RNU6-25P (88% identical), RNU6-41P (88% identical), RNU6-476P (88% identical), RNU6-1 (87% identical), RNU6-1103P (87% identical), RNU6-1145P (87% identical), RNU6-14P (87% identical), RNU6-15P (87% identical), RNU6-2 (87% identical), RNU6-20P (87% identical), RNU6-211P (87% identical), and 1288 more.